MTOR (mechanistic target of rapamycin kinase)
Diseases named in the same sentence as MTOR in open-access papers (continued):
Sharing a sentence is not in itself a finding about the gene and the disease.
oral cancer (continued). "In fact, crude drug number 107 (Binroji; areca) has been reported to induce autophagy in several cell lines, such as leukemic Jurkat T cells and oral carcinoma cells (OECM-1), Cal-27, and Scc-9 by activating the AMPK/mTOR signaling pathway after accumulating reactive oxygen species." (PMID 31163644, 2019). "Interestingly, PLK1 effect is modulated by PI3K-Akt-mTOR and MAPK pathways, both of which we have shown here were affected by ER maleate in oral cancer cells." (PMID 26934445, 2016). "Their effect on Akt/mTOR signaling, a key driver of oral carcinogenesis, has not been fully defined and hence warrants comprehensive laboratory and clinical attention, leveraging new treatment modalities for oral cancers." (PMID 40940957, 2025). "In our previous study, we proposed that chrysophanol-based therapy may decrease oral cancer progression by activating ferroptosis; however, the effect of DFO on the regulation of cell death, mTOR/PPAR-α expression, and ROS accumulation in chrysophanol-treated SAS cells is poorly understood." (PMID 35723362, 2022). "Moreover, the application of AKT, mTOR and PI3K inhibitors to patients with HNCS has been achieved only up to phase II of clinical trials, and some studies have even investigated them in combination with cetuximab or cytostatic drugs for oral cancer therapy." (PMID 34299129, 2021).
nasopharyngeal carcinoma (107 papers, 2010 to 2026). A carcinoma arising from the nasopharyngeal epithelium. "Moreover, AMP activated protein kinase (AMPK)-mammalian target of rapamycin (mTOR)-mediated activation of autophagy promotes formation of dormant polyploid giant cancer cells, which is associated with nasopharyngeal carcinoma recurrence." (PMID 40758712, 2025). "In this study, we report a rationally designed therapy to conquer BEZ235 resistance that may benefit patients with aberrant PI3K/mTOR pathway-associated nasopharyngeal carcinoma." (PMID 25762617, 2015). "It was found that goosefoot extract inhibited PI3K-Akt-mTOR signalling and cell proliferation in nasopharyngeal carcinoma CNE-1 cells." (PMID 41157091, 2025). "Previous studies have shown, upregulation of lncRNA HAGLROS enhances nasopharyngeal carcinoma development by modulating PI3K/AKT/mTOR signaling mediated by miR-100/ATG14 axis." (PMID 40756984, 2025). "An in vitro study of nasopharyngeal carcinoma showed that IGF2BP3 regulates key EMT regulatory factors by activating the AKT/mTOR signalling pathway, thus promoting the migration and invasion of nasopharyngeal carcinoma cells." (PMID 38358034, 2024). "For instance, genetic alterations in the PI3K/Akt/mTOR pathways are found in 23.4% of cases of nasopharyngeal carcinomas (NPCs), a type of malignant head and neck tumor prevalent in South China and Southeast Asia." (PMID 38272224, 2024). "mTOR inhibition via rapamycin diminishes radioresistance of radioresistant nasopharyngeal carcinoma (NPC)." (PMID 38965615, 2024). "In nasopharyngeal carcinoma cells, NaB induces mitophagy-related apoptosis by inhibiting the AKT/mTOR axis and then exerts anti-tumor effects in nasopharyngeal carcinoma." (PMID 37686278, 2023). "By mediating the HSPA5-mediated autophagy and AKT/mTOR axis, radiosensitizer exosomal miR-197-3p was reported to inhibit nasopharyngeal carcinoma (NPC) progression and radioresistance." (PMID 37275848, 2023). "It revealed that nasopharyngeal carcinoma cell lines overexpressing EpCAM had a significant increase in the level of crucial molecules of this pathway, such as mTOR and activated Akt." (PMID 35986321, 2022). "MiR-18a exerted its oncogenic effects by inhibiting SMG1 and activating the mTOR pathway in nasopharyngeal carcinoma (NPC) cells." (PMID 35223996, 2022). "Meanwhile, BA suppresses cell proliferation and induces apoptosis in nasopharyngeal carcinoma cells by suppressing PI3K/AKT/mTOR pathway." (PMID 36567856, 2022). "ANXA6 promoted autophagy by inhibiting the PI3K/AKT/mTOR signaling pathway in nasopharyngeal carcinoma." (PMID 35456441, 2022). "PNCK knockdown has been reported to regulate PI3K/AKT/mTOR signaling pathway and suppress growth and induce apoptosis of nasopharyngeal carcinoma cells in vitro and in vivo." (PMID 33801837, 2021). "Compelling evidence has indicated the vital role of lysine-specific demethylase 4 A (KDM4A), hypoxia-inducible factor-1α (HIF1α) and the mechanistic target of rapamycin (mTOR) signaling pathway in nasopharyngeal carcinoma (NPC)." (PMID 34385569, 2021). "Activation of Akt/mTOR signal axis plays a crucial role in malignant progression of various malignant tumors, including nasopharyngeal carcinoma, glioblastoma and synovial sarcoma." (PMID 32023262, 2020). "For example, inactivating mTOR by miR-3188 resulted in suppression of p-PI3K/p-AKT/c-JUN pathway, and mTOR in turn enhanced miR-3188 expression in nasopharyngeal carcinoma." (PMID 31315643, 2019). "Rapamycin, a mammalian target of rapamycin (mTOR) signaling inhibitor, inhibits cancer cell proliferation and tumor formation, including in nasopharyngeal carcinoma (NPC), which we proved in a previous study." (PMID 26202311, 2015). "PIK3CA gene mutation and amplification are observed frequently in NPC, especially in advanced stages of disease, indicating a potential therapeutic effect of the dual PI3K/mTOR inhibitor in nasopharyngeal carcinoma." (PMID 25762617, 2015).
nasopharyngeal carcinoma (continued). "During the preparation of this paper, a very recent study reported that exogenous LIF activates the mTOR pathway in nasopharyngeal carcinoma cell lines, which is consistent with our findings." (PMID 24553191, 2014). "LMP2A was shown to activate PI3K-AKT- and mTOR signaling in several cell lines, including a nasopharyngeal carcinoma line, and in vivo, in B-cells of LMP2 transgenic mice." (PMID 24710474, 2012). "Additionally, EBV-miR-BART1-5p activates the AMPK/mTOR/HIF1 pathway in nasopharyngeal carcinoma cells, promoting the aerobic glycolysis process." (PMID 38686046, 2024). "Indeed, the mTOR signaling dysregulation is involved in multiple human cancers, including lung, breast, cervical, colon, reproductive, and bone cancers, as well as nasopharyngeal carcinoma." (PMID 36428613, 2022). "However, it has been reported that hsa-mir-3188-3p decreases the proliferation of the EBV-positive nasopharyngeal carcinoma cell line (HONE1-EBV) by interacting with mTOR." (PMID 33805769, 2021). "EBV LMP2A has been associated with nasopharyngeal carcinoma (NPC) and constitutively activates mTOR growth regulatory pathways to mediate cell transformation via PI3K activation, as the PI3K inhibitor Wortmannin specifically blocked Akt phosphorylation in LMP2A-expressing cells." (PMID 27231932, 2016). "Recently, mTOR signaling was investigated in human primary nasopharyngeal carcinoma (NPC) and it was found that mTOR involvement in NPC shows high impact on the behavior of CSCs thus playing a potential role in the regulation of CSC environment." (PMID 32351329, 2020). "It will be interesting to investigate whether LIF also activates the mTOR pathway through AKT in nasopharyngeal cancer, whether the activation of LIF-AKT-mTOR pathway exists in other types of tumors, and plays an important role in tumorigenesis in future studies." (PMID 24553191, 2014). "Brevilin A and Arnicolide D can activate the Caspase signalling pathway by regulating cell cycle proteins, inhibit the PI3K/AKT/mTOR and STAT3 signalling pathways, and thus inhibit the nasopharyngeal carcinoma cell growth." (PMID 41157091, 2025). "In malignant tumors of the head and neck (such as oropharyngeal cancer and nasopharyngeal carcinoma), TRIB3 can function to regulate cell functions via PI3K / AKT / mTOR signaling pathway." (PMID 39869954, 2025). "The results of their network analysis experiments showed that the anti-nasopharyngeal carcinoma effect of CEP was related to eight core targets such as EGFR, AKT1, PIK3CA and mTOR." (PMID 41368570, 2025). "SNG inhibits the growth of human nasopharyngeal carcinoma 5–8 F cells, induces autophagy, and suppresses proliferation by activating AMPK/mTOR signaling." (PMID 39239653, 2024). "SNG, in combination with 5-fluorouracil, synergistically inhibits the growth of nasopharyngeal carcinoma grafts in vivo, inducing autophagy and apoptosis related to the PI3K/AKT/mTOR signaling pathway." (PMID 39239653, 2024). "NOS1 can also activate the AKT/mTOR signaling pathway through the S-nitrosylation of PTEN, thereby inhibiting autophagy in nasopharyngeal carcinoma cells." (PMID 38877096, 2024). "Additionally, it showed encouraging anti-tumour activity in acute myeloid leukaemia (AML) and an ability to inhibit both AKT and mTOR signalling in nasopharyngeal carcinoma (NPC) cell lines." (PMID 36765661, 2023). "In nasopharyngeal carcinoma (NPC), enhanced EpCAM expression downregulated PTEN while promoting the phosphorylation of AKT, mTOR, p70S6K and 4EBP1." (PMID 36369033, 2022). "EBV activates AMPK/mTOR/HIF1 pathway to promote glycolysis and induces angiogenesis in nasopharyngeal carcinoma cells." (PMID 35432224, 2022). "At later time points, LMP1 and LMP2A further activate the PI3K/mTOR pathway, and LMP1 also promotes glutamine uptake in nasopharyngeal carcinoma (NPC) cells." (PMID 35108325, 2022).
nasopharyngeal carcinoma (continued). "In nasopharyngeal carcinoma cells, pro-apoptotic autophagy is inhibited by NOS1 overexpression through the activation of the mammalian target of rapamycin (mTOR) and upstream AKT signaling pathways by S-nitrosation of the phosphatase and tensin homolog (PTEN)." (PMID 34200849, 2021). "On the other hand, capsaicin also induces G1 arrest and apoptosis of nasopharyngeal cancer cells through mitochondrial depolarization and acting on specific pathways (PI3K/mTOR) and molecules (caspase-3, Bcl-2)." (PMID 33609025, 2021). "The inhibition of mTOR/p70S6k pathway, for the activation of autophagy was also exerted by wogonin (50 μM), a flavone from Scutellaria baicalensis, in human nasopharyngeal carcinoma cells (NPC-TW076 and NPC-TW039)." (PMID 32927836, 2020). "LMP1 has been reported to activate lipogenesis via mTOR and SREBP1 in nasopharyngeal carcinoma (NPC) cells, which typically express the latency II program." (PMID 31518366, 2019). "Reduced PTEN and PPP2R2B expression correlated with activated AKT/mTOR and PDK1/MYC pathways and conferred considerable BEZ235 resistance in nasopharyngeal carcinoma." (PMID 25762617, 2015). "BEZ235 significantly inhibits cell proliferation in nasopharyngeal carcinoma both in vitro and in vivo by blocking the PI3K/AKT/mTOR pathway." (PMID 25762617, 2015). "Reduced PTEN and PPP2R2B expression correlated with activated AKT/mTOR and PDK1/MYC pathways, which can confer considerable BEZ235 resistance in nasopharyngeal carcinoma." (PMID 25762617, 2015). "To ascertain a therapeutical approach of nasopharyngeal carcinoma (NPC), we hypothesized NVP-BEZ235, a novel and potent imidazo[4,5-c] quinolone derivative, that dually inhibits both PI3K and mTOR kinases activities, had antitumor activity in NPC." (PMID 23533654, 2013). "In nasopharyngeal carcinoma, the overexpression of Chromosome 2 open reading frame 40 (C2orf40) regulates the PI3K/AKT/mTOR pathway, significantly reducing the protein expression levels of key cell cycle regulators, including Cyclin-dependent kinase 1 (CDK1), Cyclin E1, and Cyclin B1." (PMID 40725100, 2025). "Additionally, TNC promotes epithelial–mesenchymal transition in nasopharyngeal carcinoma and activates the PI3K/AKT/mTOR signaling pathway, collectively supporting its role as an oncogene." (PMID 41227351, 2025). "In nasopharyngeal carcinoma cells, PARP-1 can activate autophagy through the AMPK/mTOR pathway such that interfering with PARP-1 or AMPK activity can suppress autophagic activity and increase CNE-2 nasopharyngeal carcinoma cell sensitivity to radiation treatment." (PMID 37351512, 2023). "Also, it confirms that activation of the Akt/mTOR signaling pathway is necessary for EMT, resulted from EpCAM overexpression in nasopharyngeal carcinoma cells." (PMID 35986321, 2022). "In addition, rapamycin with AKT inhibitors can alter the AKT/mTOR pathway to regulate EMT, stemness, and metastasis in nasopharyngeal carcinoma cells." (PMID 34255431, 2021). "In this study, using an integrated analysis of acquired BEZ235-resistant nasopharyngeal carcinoma cells, we demonstrate that DNA methyltransferase is a key modulator and a common node upstream of the AKT/mTOR and PDK1/MYC pathways, which are activated in cancer cells with acquired BEZ235 resistance." (PMID 25762617, 2015). "On the other hand, miR-BART1 can also regulate the AMPK/mTOR/HIF-1 pathway in a PTEN-independent manner by directly targeting the α1 catalytic subunit of AMPK (AMPKα1), promoting anomalous aerobic glycolysis and angiogenesis in nasopharyngeal carcinoma (NPC) cells." (PMID 40302035, 2025).
esophageal squamous cell carcinoma (105 papers, 2013 to 2026). Esophageal squamous cell carcinoma (ESCC) is a type of esophageal carcinoma (EC) that can affect any part of the esophagus, but is usually located in the upper or middle third. "Luo et al12 found a similar phenomenon in esophageal squamous cell carcinoma (ESCC), where the abnormal activation of the P13K/Akt/mTOR signaling pathway can cause abnormal growth, differentiation, migration, metabolism, and proliferation of ESCC." (PMID 39634439, 2024). "WTAP positively regulates the expression of m6A target PTP4A1, activates the AKT mTOR pathway, and promotes esophageal squamous cell carcinoma (ESCC) cell proliferation." (PMID 41256854, 2025). "It efficiently suppressed the proliferation of both imatinib-sensitive and -resistant CML cells via the mechanistic target of rapamycin (mTOR)-Unc-51-like kinase 1 (Ulk1) pathway and can sensitize esophageal squamous cell carcinoma to radiotherapy." (PMID 41425251, 2025). "Metformin was shown to induce autophagy through the inactivation of the STAT3 and mTOR pathways in esophageal squamous cell carcinoma." (PMID 40176890, 2025). "The ubiquitin-like with plant homeodomain and ring finger domains 1 (UHRF1) regulates cancer signaling pathways in esophageal squamous cell carcinoma (ESCC) by influencing the PI3K/Akt/mTOR pathway, crucial for tumor growth and resistance to therapies." (PMID 38813086, 2024). "Echinatin inhibits the growth and invasion of esophageal squamous cell carcinoma by inactivating the Akt/mTOR signaling pathway." (PMID 38668684, 2024). "In esophageal squamous cell carcinoma, dihydroartemisinin weakens p‐mTOR, p‐p70S6K, and p‐RPS6 to inhibit tumor growth." (PMID 38988047, 2024). "The mTOR inhibitor everolimus and its analogs are used to treat various solid tumors, such as esophageal squamous cell carcinoma, lung cancer, renal cell carcinoma, and prostate cancer." (PMID 37173935, 2023). "Recent studies have shown that PKMYT1 contributes to tumor progression via AKT/mTOR signaling pathway in esophageal squamous cell carcinoma." (PMID 36793346, 2022). "Here, the authors report that this modification regulates the translation of proteins in both the mTOR and negative regulators of autophagy pathways, resulting in the progression of esophageal squamous cell carcinoma." (PMID 35304469, 2022). "Oxidative stress induced by sulforaphane inactivates mammalian target of rapamycin (mTOR) in esophageal squamous cell carcinoma cells, thereby increasing the exosomal yield." (PMID 36082080, 2022). "proved that CHRNB4 knockdown can inhibit the proliferation of esophageal squamous cell carcinoma via the Akt/mTOR and ERK1/2/mTOR pathways by cell counting kit-8, cloning formation assay, and Western blot." (PMID 34912722, 2021). "FOXD2-AS1 harbored miR-195 to activate Akt/mTOR pathway to activate esophageal squamous cell carcinoma progression." (PMID 33869779, 2021). "Knockdown of PSMD7 inhibits tumorigenesis and induces cell apoptosis in esophageal squamous cell carcinoma (ESCC) via the mTOR/p70S6K pathway." (PMID 33687056, 2021). "Dual inhibition of the PI3K/AKT/mTOR pathway with MK2206 and BEZ235 caused cell cycle arrest and enhanced apoptosis through the downstream effectors SKP2, MCL-1, and cyclin D1 in esophageal squamous cell carcinoma cells." (PMID 33659215, 2020). "A published study uncovered that miR-503 triggered autophagy in esophageal squamous cell carcinoma via the PKA/mTOR pathway." (PMID 33093470, 2020). "Several studies suggest that miR-100 directly targets the mTOR mRNA 3′UTR and represses mTOR expression in esophageal squamous cell carcinoma and chronic vascular inflammation." (PMID 31358056, 2019). "Previous study reported that PRDX1 was functionally involved in Akt/mTOR in esophageal squamous cell carcinoma." (PMID 29492195, 2018).